SERP1 (stress associated endoplasmic reticulum protein 1)
Diseases named in the same sentence as SERP1 in open-access papers (continued):
Sharing a sentence is not in itself a finding about the gene and the disease.
Obesity (1 paper, 2022). Accumulation of substantial excess body fat. "Two DEGs associated with obesity in humans from the magenta module that merit further study are stress-associated endoplasmic reticulum protein 1 (Serp1) and UDP-glucose glycoprotein glucosyltransferase 1 (Uggt1)." (PMID 35945490, 2022).
viral infections (1 paper, 2019). "The role of SERP1 in viral infections is poorly characterized." (PMID 31461934, 2019).
ZIKV infection (1 paper, 2021). "Three robust patterns were identified: genes, such as HSPA5, that were upregulated in DENV infection and downregulated in ZIKV and VEEV infections; genes like NRBF2 that were upregulated only during ZIKV infection; and genes, such as SERP1, that were downregulated only in VEEV infection." (PMID 33788849, 2021).
infection (10 papers, 2013 to 2025). The state of being infected such as from the introduction of a foreign agent such as serum, vaccine, antigenic substance or organism. "The Shope fibroma Myxomavirus variant has a scrambled Serp-1 gene sequence, and produces only a benign self-limiting infection in rabbits." (PMID 32244484, 2020). "When the Serp-1 gene is deleted in myxomavirus, this lethal European rabbit infection becomes benign and the blockade of rabbit immune cell responses, that are produced in response to myxoma infection, is lost." (PMID 37759793, 2023). "When given as a delayed treatment in the MA30SARS infection model, Serp-1 again improved the outcomes at a lower dose." (PMID 37759793, 2023). "We report here a systematic examination of the role of the gut bacterial microbiome in MHV-68 infection and on Serp-1 and Serp-1-derived S-7 peptide treatment in MHV-68 infections." (PMID 32047224, 2020). "Infection with Nc-Spain1H also upregulated expression of SERP-1 at 10 dpi, that was maintained at 20 dpi." (PMID 32552750, 2020). "In Myxomavirus infections, the deletion of Serp-1 or Serp-2 genes modifies this highly lethal infection in European rabbits (Oryctolagus cuniculus) to a benign local infection." (PMID 32244484, 2020). "The virus titers from the SERP1 knockout cells were significantly increased (16-fold; p = 0.03) at day two post-infection, compared with the titers from the infected WT cells." (PMID 31461934, 2019). "Oral dental plaques collected post-5th infection demonstrated that all the mice were positive for P. gingivalis in Pg, Pg + BA and Pg + BA + Serp-1 groups and 4 out of 5 mice in the P. gingivalis + BA + M-T7 group were positive." (PMID 25354050, 2014). "The IgG antibody levels in mice treated with Serp-1 and M-T7 with BA were lower than in untreated mice with P. gingivalis-infection (P = 0.37)." (PMID 25354050, 2014). "Like other secreted MYXV proteins, Serp1 is glycosylated by cellular enzymes during infection." (PMID 40872858, 2025). "In European rabbits, infection with MYXV missing both copies of the Serp-1 gene is attenuated." (PMID 40872858, 2025). "The suppression of gut bacteria by the oral administration of an antibiotic cocktail worsened MHV-68 infection and blocked Serp-1 treatment efficacy, indicating that the Serp-1 therapeutic efficacy in this MHV68 model was dependent upon an intact gut microbiota." (PMID 37759793, 2023). "In a word, the interaction between PABPC4, SERP1, and ORFV ORF047 will provide several pieces of information on ORFV infection and replication." (PMID 33499896, 2021). "16S rRNA gene amplicon sequencing was performed on DNA extracts derived from the large intestines of individual mice 3 days post-infection with MHV-68 and after treatment with Serp-1 or S-7." (PMID 32047224, 2020). "As previously reported, Serp-1 and S-7 peptide improved survival with 60% of mice surviving to 150 days after MHV-68 infection." (PMID 32047224, 2020). "In prior work, treatment with myxomavirus-derived Serp-1 or a derivative peptide S-7 (G305TTASSDTAITLIPR319) induced immune protection, reduced disease severity and improved survival after MHV-68 infection." (PMID 32047224, 2020). "Thus, the efficacy of Serp-1 or S-7 treatment and protection in lethal MHV-68 infections was dependent on the gut bacterial microbiome." (PMID 32047224, 2020). "Neither Serp-1 nor M-T7 treatment reduced infection, but IgG antibody levels in mice treated with Serp-1 and M-T7 were reduced." (PMID 25354050, 2014). "In these human cell lines, both M029-minus virus constructs could bind, enter and initiate the synthesis of early viral protein (eg M-T7), however, the infection was then aborted and no synthesis of late protein (Serp-1) could be detected." (PMID 23853588, 2013).
infection (continued). "In a clinical trial, Serp-1 proved safe with minimal, if any, side effects and no major adverse cardiovascular events (MACE score = 0), and specifically with no detected increase in thrombosis or bleeding and no increased infections." (PMID 32244484, 2020).
tumor (6 papers, 2013 to 2025). "The inhibition of tumor growth by Serp-1 was associated with a significant decrease in splenocyte MDSC counts as assessed by flow cytometry, without reductions in other splenocyte subpopulations." (PMID 37759793, 2023). "Stress-associated endoplasmic reticulum protein 1 (SERP1) is a gene induced by endoplasmic reticulum (ER) stress and a major contributor to multiple tumor types." (PMID 34613934, 2021). "We have postulated that the viral anti-inflammatory serpins, such as Serp-1, and CMPs such as M-T7 will block tumor associated leukocyte activity and tumor progression." (PMID 25798214, 2013). "However, the results of this study differ from previous findings that high SERP1 expression is associated with poor tumor prognosis." (PMID 34613934, 2021). "miR-124 affects the ability of tumor cells to survive under O2 and/or nutrient deprivation in part by directly regulating SERP1, which is among factors involved in cell proliferation and survival under stress." (PMID 26041995, 2015). "This study suggested that Serp-1 may contribute to the oncolytic tumor suppressing activity of myxomavirus." (PMID 37759793, 2023). "Serp-1 and NSP both also reduced tumor-associated macrophage infiltration." (PMID 37759793, 2023). "Recently, SERP1 has been reported to play an important role in tumor cell survival." (PMID 34613934, 2021). "Moreover, our study found that SERP1 expression levels positively correlated with most immune cell markers suggesting the positive role of SERP1 in modulating tumor immunology in SKCM." (PMID 34613934, 2021). "With these studies we have explored the potential of anti-inflammatory viral serpins and chemokine modulators in cancer treatment, examining the efficacy of Serp-1, neuroserpin (a related mammalian serpin), and M-T7 for inhibition of selected human tumor cell lines in immunodeficient NOD/SCID mice." (PMID 25798214, 2013). "Exogenous uPA clearly blocked the anti-inflammation/antitumor function of Serp-1 in this cancer model, supporting the hypothesis that Serp-1 exerts anti-tumor function by inhibiting uPA activity." (PMID 25798214, 2013). "The cancer suppressive effects of Serp-1 observed in vivo thus is proposed to involve interaction of different cell types within the tumor, including cancer cells and stromal cells such as fibroblasts, vascular endothelial cells and a range of inflammatory cells." (PMID 25798214, 2013). "Among highly perturbed gene pairs across multiple tumor types, we noted CXXC1, HSPA5, GSK3A, SERP1, PDIA6, FKBP14, and SCH1, which showed multiple co‐expression changes." (PMID 34698427, 2021). "We began with an assessment of the capacity of the antiinflammatory serpins, Serp-1 and NSP, to modify growth of a range of human cancer tumor cell lines when implanted in NOD/SCID mice." (PMID 25798214, 2013). "As Serp-1 inhibits both thrombolytic serine proteases tPA and uPA and also thrombotic proteases FX and FII, whereas NSP inhibits only tPA and uPA, we have posited that the majority of the anti-tumor activity is dependent upon the inhibition of the thrombolytic proteases tPA and uPA." (PMID 25798214, 2013). "With the addition of uPA to the tumor implants, Serp-1 treatment no longer significantly decreased macrophage infiltration and MDSC mobilization (P= NS), nor inhibited tumor growth in these mice (P=NS), although there was a trend toward a reduction." (PMID 25798214, 2013).
cancer (3 papers, 2011 to 2021). A tumor composed of atypical neoplastic, often pleomorphic cells that invade other tissues. "Based on TCGA, SERP1 mutated lowly in SKCM via pan-cancers analysis." (PMID 34613934, 2021). "By analyzing The Cancer Genome Atlas (TCGA) and Genotype-Tissue Expression (GTEx) database, we obtained the expression of SERP1 RNA in pan-cancer." (PMID 34613934, 2021). "We focused on TAGLN2 and not the top ranked gene (SERP1), because the latter was not reported to be associated with carcinoma." (PMID 21378409, 2011). "Future study aimed to characterize the functional status of inflammatory cells including MDSCs and TAMs, as well as to assess the function of uPA/uPAR in these tumors might shed more lights on the mechanism of the anti-cancer activity of Serp-1 and neuroserpin." (PMID 25798214, 2013). "Thus, Serp-1 may not directly inhibit cancer cell proliferation." (PMID 25798214, 2013). "Serp-1 acts as a suicidal substrate for uPA and thus may not necessarily directly interrupt uPA signaling or may interrupt cell activation, invasion or even signaling to different degrees in cancer cells or in inflammatory response cells that support cancer cell growth and invasion." (PMID 25798214, 2013).
vasculopathy (2 papers, 2021 to 2023). "In this transplant vasculopathy model, Serp-1 treatment improved inflammation and intimal hyperplasia." (PMID 37759793, 2023). "We are investigating a Myxomavirus derived immune modulating serpin, Serp-1, as a new class of immune modulating therapeutics for vasculopathy and lung hemorrhage." (PMID 33665212, 2021). "Serp-1 blocked plaque growth after aortic isograft transplant and after wire-induced injury in PAI-1-deficient mice, indicating that PAI-1 expression is not required for Serp-1 to block the development of vasculopathy." (PMID 37759793, 2023).
cardiovascular disease (1 paper, 2011). "Firstly, due to the strong immune suppressing effects of certain MYXV proteins, several secreted virus-encoded immunomodulators (e.g. Serp-1) are being developed to treat systemic inflammatory syndromes such as cardiovascular disease in humans." (PMID 21658227, 2011).
genetic disorder (1 paper, 2022). "While Serp-1 treatment has been examined in a wide range of animal models of acute inflammation-induced disease, this is the first study of Serp-1, and specifically PEGSerp-1, as a treatment in a genetic disorder with chronic inflammation as a hallmark symptom." (PMID 35625891, 2022).
infectious disease (1 paper, 2016). A disorder directly resulting from the presence and activity of a microbial, viral, or parasitic agent in humans. "Additionally, the disease/function networks that associated with AGE downregulated Casp1, Tlr3, Serp1, Irf1, Irf5, and Irf7 genes were involved in the antimicrobial response, inflammatory response, and infectious diseases." (PMID 27734935, 2016).
SERP1 also shares sentences with these, for which no sentence is quoted: asthma (1 paper); atherosclerosis (1); autoimmune disease (1); diabetes (1); fibrosis (1); glioma (1); inflammation (1); inflammatory bowel disease (1); multiple sclerosis (1); myocardial disease (1); papillary thyroid cancer (1); prostate carcinoma (1); rectal cancer (1); rheumatoid arthritis (1); Spinal Cord Trauma (1); ST Elevation Myocardial Infarction (1).